CD14 (CD14 molecule)
Diseases named in the same sentence as CD14 in open-access papers (continued):
Sharing a sentence is not in itself a finding about the gene and the disease.
atherosclerosis (continued). "Athero-protective role of the 129 Lbp is supported by the observed association between serum Lbp levels and CAD in humans and well-documented links among chronic infections, inflammation, and atherosclerosis, as well as roles of LBD, CD14 and TLR in atherosclerosis." (PMID 24586312, 2014). "We sought to determine if CD14 deletion would attenuate aneurysm formation in a murine AAA model that was independent of atherosclerosis, hypertension, and hyperlipidemia." (PMID 23537804, 2013). "In contrast to the data suggesting a lack of involvement of CD14 in atherosclerosis, we provide compelling evidence that CD14 is intimately involved in AAA formation." (PMID 23537804, 2013). "Our overall data suggested that the altered expression of a number of miRNAs in CD14+ and CD16+ monocytes play an essential role in the development of the endothelial dysfunction present in RA patients, which in turn, heralds the progression of atherosclerosis and drives the development of CVD." (PMID 32188016, 2020). "To determine the origin of transcripts in cell types involved in atherosclerosis, we mapped the TSS using Rapid Amplification of cDNA Ends (RACE) in primary human macrophages, aortic endothelial cells (HAEC), monocytes and peripheral blood mononuclear cells (PBMC) depleted of CD14+ monocytes." (PMID 27187934, 2016). "However, Bjorkbacka et al9 showed that deletion of CD14 had no impact on aortic root atherosclerosis in apoE−/− mice." (PMID 23537804, 2013). "Human and microbial HSP60activate vascular endothelial cells and macrophages directly through CD14 and p38 mitogen-activated protein kinasesignalling pathway in a similarmanner as bacterial lipopolysaccharide (LPS), leading to IL-6 and TNF-αsecretion and promotion of atherosclerosis." (PMID 18551190, 2008). "Other pathogens studied inrelation to atherosclerosis are Bacteroidesforsynthus, where the protein A secreted by the bacterium acts through CD14and TLR2 ligations to induce atherosclerosis, whereas in the case of Streptococcus mutans it is the proteinAgI/II that acts through CD14 and TLR4." (PMID 18551190, 2008). "Further, circulating leukocyte-derived MV levels might predict subclinical atherosclerosis in asymptomatic individuals, and it was thus unexpected that the patients did not have higher levels of CD14+ MVs, and that these MV phenotypes were unaffected by inflammation." (PMID 30425991, 2018). "Finally, CD14-positive magnetic bead sorting skewed the analyzed monocyte compartments towards classical CD14++CD16− and intermediate CD14++CD16+ monocytes, and partly disregarded the nonclassical CD14+CD16++ monocyte subset, which is considered less important for atherosclerosis development." (PMID 29203885, 2017). "Our results indicate that the activation of CD14, TLR4, and TLR2 on monocytes and macrophages by a very early form of oxidized LDL induces the secretion of pro-inflammatory cytokines such as IL-1β and IL-6, which may contribute to or exacerbate inflammatory responses during atherosclerosis." (PMID 20946675, 2010). "Given that hypoglycemia, assessed by CGM, is associated with atherosclerosis in non-DM patients, hypoglycemia and associated glucose fluctuations could explain the significant correlation that was observed in the non-DM patients between the MAGE scores and CD14++CD16+ monocyte levels." (PMID 28789689, 2017). "CD14 enriched cells derived from two groups of CKD patients with different progression of atherosclerosis and two groups of CVD patients with non-CKD-related atherosclerosis were analyzed." (PMID 38389898, 2024). "Intermediate monocytes (CD14++/CD16+) and non-classical monocytes (CD14+/CD16+) have been shown to have the characteristics of activated cells, exhibit a pro-inflammatory nature and may contribute to atherosclerosis." (PMID 37443712, 2023).
atherosclerosis (continued). "Intermediate (CD14+CD16+) and non-classical or inflammatory (CD14+CD16++) subsets produce large amounts of proinflammatory mediators and are up-regulated in many inflammatory disorders, such as rheumatoid arthritis, atherosclerosis, bacterial sepsis and various hepatic diseases." (PMID 25314914, 2014).
asthma (89 papers, 2006 to 2025). "Stacked bar plots revealed disease‐associated shifts: asthma PBMCs exhibited reduced MHC‐II‐high CD14+ monocytes (5.8% vs." (PMID 40951943, 2025). "Significant markers associated with a higher asthma risk include CD14 on CD33br HLA DR+ CD14dim, commonly found on MDSCs and macrophages." (PMID 40551049, 2025). "Our study is in agreement with findings of this study in which CD14 gene polymorphism was associated with an increase in serum CD14 levels and a decrease in serum IgE levels in patients with allergic diseases such as asthma and allergic rhinitis." (PMID 41438035, 2025). "In the ADEM-study we found an interaction between bacterial colonisation of the upper airways, genetic variants in the TLRs and CD14 genes, and the development of asthma at age 6 years." (PMID 37013496, 2023). "A protective synergistic effect of soluble CD14 levels and breastfeeding on the risk of asthma was reported in a large prospective cohort study, especially in children of mothers without a history of atopic disease." (PMID 37730734, 2023). "For example, there was an interaction between bacterial colonisation of the upper airways, genetic variants in the TLRs and CD14 genes, and the development of asthma at age 6 years." (PMID 37013496, 2023). "These contradicting findings are more likely due to differences between the pathophysiology of asthma and AR, as well as the impact of microorganisms and allergen exposure associated with CD14 and CD14 gene polymorphisms." (PMID 37286630, 2023). "Some DEGs from this comparison, such as Fos, Jun, Hes1, Cd14, and C3, have been associated with asthma pathogenesis." (PMID 35627266, 2022). "Al Sulaimani studied the genetic basis of asthma in Saudis and demonstrated three polymorphisms of CD14 promoter gene in asthma children." (PMID 29951546, 2018). "Childhood-onset and adult-onset of asthma showed significant difference in allergen sensitivity as well as genetic background with respect to CD14 polymorphism." (PMID 29937881, 2017). "The gene encoding Cluster Differentiation antigen (CD14) is localized on chromosomal 5q31.1 region which is associated with both asthma and total serum IgE concentration." (PMID 29937881, 2017). "We examined the associations between single-nucleotide polymorphisms (SNP) in the TLR/CD14 genes and asthma, and their interaction with proxies of microbial exposure (childhood farm exposure and childhood rural environment)." (PMID 28262750, 2017). "The homozygous CC genotype and also C allele at CD14 -159 were predominant in patients with childhood onset of asthma compared to those of adult onset and in patients with moderate and severe form of the disease than those with a mild form of asthma." (PMID 29937881, 2017). "There is paucity of data regarding aero-allergen sensitization among atopic patients in the Kolkata metropolitan area, particularly in asthma and CD14 polymorphisms in the same population." (PMID 29937881, 2017). "There have been a limited number of studies in adults showing an association between CD14 polymorphisms and several lung phenotypes such as asthma and allergy, wheeze, pulmonary tuberculosis and pulmonary function." (PMID 28302109, 2017). "Unfortunately we did not have an objective marker of microbial exposure such as endotoxin levels in the current study to fully examine the relationship between CD14 and microbial exposure and asthma risk." (PMID 28262750, 2017). "Two SNPs in the CD14 gene (−260C/T and -159C/T) have been shown to be associated with asthma susceptibility in French, Dutch and English populations." (PMID 27495363, 2016). "Our data indicated that risk alleles located in ADAM33 rs2280090 and rs3918396, IL4 rs2243250 and CD14 rs2569190 are associated in allergy, asthma, and other related phenotypic traits such as wheezing and atopy." (PMID 27624002, 2016).
asthma (continued). "We observed an additional suggestive association between CD14 rs2569190: individuals with CD14 rs2569190 G allele have an increased risk of having an asthma diagnosis (z = 3.214; p = 1.36*10−3)." (PMID 27624002, 2016). "We also found a suggestive evidence supporting the association of CD14 rs2569190 with asthma diagnosis." (PMID 27624002, 2016). "IL4 rs2243250 was associated with increased FEV240 (Forced Expiratory Flow Volume after 240s of hypertonic saline inhalation; p = 4.81*10−4) and CD14 rs2569190 was associated with asthma diagnosis (p = 1.36*10−3)." (PMID 27624002, 2016). "Epidemiological studies have evaluated numerous polymorphisms in TLR2, TLR4 and CD14 in relation to asthma and similar phenotypes and some were significantly associated with high asthma prevalence, risk or severity." (PMID 27495363, 2016). "Previous studies have shown that polymorphisms of CD14 gene are involved with some inflammatory diseases, such as asthma, inflammatory bowel disease, ulcerative colitis and Crohn's disease." (PMID 25394369, 2014). "We reviewed the literature on the relationship between CD14 and TLRs (polymorphisms) and asthma in Caucasian children." (PMID 23496969, 2013). "For example, it has been demonstrated that the direction of the relation between a CD14 polymorphism and asthma was dependent on endotoxin exposure." (PMID 23496969, 2013). "Firstly, by systematic evaluation of the available literature, our review provides an efficient and comprehensive summary of CD14 and TLRs polymorphisms in relation to childhood asthma." (PMID 23496969, 2013). "Previous studies have shown that depending on the CD14 polymorphism, the association between asthma and endotoxin can vary and include being a protective factor as well as a risk factor." (PMID 22966977, 2012). "As of 2010, over 250 different genes have been associated with asthma, including cluster of differentiation 14 (CD14)." (PMID 21745379, 2011). "This meta-analysis provides a comprehensive examination of the available evidence concerning the association between the CD14 -260C>T polymorphism and asthma susceptibility." (PMID 21745379, 2011). "The majority of investigators examining the impact of genetics on responses to environmental microbial exposures in childhood asthma have focused on polymorphisms in CD14, TLR4, and TLR2." (PMID 22151743, 2011). "A single nucleotide polymorphism (SNP) in the CD14 gene at position -260 (also known as -159) C>T has been inconsistently associated with asthma." (PMID 21745379, 2011). "Of note, for CD14, a pattern recognition receptor in the endotoxin-induced immune response, associations between the CD14-159 polymorphism and asthma and atopy differ at high versus low levels of endotoxin exposure." (PMID 17450233, 2007). "They suggested that specific single nucleotide polymorphisms (SNPs) in the Cd14 promoter gene might be associated with NP pathogenesis and asthma incidence." (PMID 38678138, 2024). "Moreover, multiple studies have characterized a similar interaction between asthma, CD14 variants and environmental endotoxin exposure, a marker of microbial exposure capable of inducing severe airway inflammation." (PMID 31921716, 2019). "Also, a link between polymorphism in CD14 gene has been associated with atopy, asthma, and IgE levels." (PMID 29867994, 2018). "CD14 is a genetic factor for individual variant susceptibility, and its role has been investigated in many diseases, such as inflammatory bowel disease, Helicobacter pylori infection-related gastric carcinoma, asthma and TB." (PMID 29298876, 2018). "CD14 has been identified as a genetic factor for individual variant susceptibility, and its role has been investigated in many diseases, such as inflammatory bowel disease, asthma and TB." (PMID 29298876, 2018). "We investigated whether childhood farm exposure or childhood rural environment modified the association between the TLR and CD14 SNPs and risk of early- and late-onset asthma." (PMID 28262750, 2017).
asthma (continued). "As TLRs and CD14 were heavily involved in the recognition of microbial compounds, genetic variation of these receptors can have a substantial effect on Th1/Th2 immune balance that directly influence the risk of asthma." (PMID 28262750, 2017). "Our data confirmed the role of CD14 in the predisposition to asthma in Turkish children." (PMID 27624002, 2016). "Severe asthma has also been linked to the presence of Th17-related cytokines, and CD14++CD16+ monocytes may mediate Th17 cell expansion." (PMID 26658828, 2015). "The CD14 gene is present in the major susceptibility region (5q31-33) for atopy and asthma." (PMID 24524443, 2014). "The CD14 C allele was found to be more common in asthma patients who were allergic to house dust." (PMID 24524443, 2014). "Polymorphisms in CD14 and levels of soluble CD14 (sCD14) have been implicated in childhood asthma." (PMID 23496969, 2013). "The relation between childhood asthma and polymorphisms in CD14 was studied in 17 studies." (PMID 23496969, 2013). "Therefore, it is important to study the influence of gene-gene interaction as well as other polymorphisms in CD14 on the effects of this locus on asthma susceptibility." (PMID 21745379, 2011). "An antagonistic interaction has been demonstrated between CD14 and endotoxin exposure: homozygotes for the T allele appear to be protective for asthma at low levels of endotoxin exposure, but may increase asthma risk at high levels of endotoxin exposure." (PMID 21745379, 2011). "Also located on chromosome 5, the C-159T single nucleotide polymorphism (SNP) within the cluster of differentiation (CD14) gene has been associated with asthma, asthma severity, and total serum IgE." (PMID 21320344, 2011). "Another gene is CD-14, which is indicated as an example of gene-environment correlation in asthma, and genes encoding beta-defensin 1 and matrix metalloproteinases may also be involved in the relationship between caries and asthma." (PMID 33541418, 2021). "Ultimately, the discovery of the CD14 molecule, a receptor of bacterial endotoxin, is interesting as gene–environment interactions of raw milk consumption and polymorphisms associated with this gene have been discussed controversially for childhood onset asthma." (PMID 28858242, 2017). "Regulation of CD14 gene expression and serum level of sCD14 might affect the proportion of Th1 to Th2 cells, thereby influencing IgE responses and associated inflammatory phenotype in asthma." (PMID 29937881, 2017). "CD14 rs2569190 may be exemplary for the relevance of polymorphisms in relation to asthma." (PMID 23496969, 2013). "One study showed that of the protective farm related factors that were associated with asthma (pig farming, farm milk consumption, frequent stay in animal sheds, and child’s involvement in haying), only being a farm child in general was associated with higher expression levels of CD14." (PMID 23496969, 2013). "The CD14-159 C > T polymorphism, a SNP at position -159 in the promoter region of the gene encoding this pattern recognition receptor, is associated with elevated plasma/serum concentrations of soluble CD14, an increased risk for myocardial infarction and a decreased risk for allergies and asthma." (PMID 23046822, 2012). "On the other hand, three bacteria played a predisposing role in asthma through the mediating effects of HLA DR+ natural killer %natural killer, and CD16 on CD14+ CD16+ monocyte and CD40L receptor levels." (PMID 40191192, 2025). "The results show that both signaling pathways are more prominent in asthma groups than control group, especially for CD14+ monocytes." (PMID 41550933, 2025). "We found that at baseline, asthma patients exhibited higher percentages of total CD14+ as well as CD14+CD16− and CD14+CD16+ monocyte subsets compared to nonasthmatic control subjects (left)." (PMID 40697948, 2025).
asthma (continued). "Asthma patients exhibited increased numbers of CD14+CD2hi monocytes (Fig E5, E, left), but omalizumab treatment did not significantly alter their numbers in both those with and without response (Fig E5, E, right)." (PMID 40697948, 2025). "These subsets were identified as CD14++CD16−, CD14++CD16+, and CD14+CD16++, with the importance of the CD14++CD16+ in disease states such as asthma being recognised." (PMID 37240103, 2023). "Polymorphisms in CD14 rs2569190 and TLR2 rs13150331 in asthma patients influences the microbial composition." (PMID 36532717, 2022). "Asthma patients with genotypes AG/GG at CD14 rs2569190 showed elevated levels of neutrophils and lower levels of Prevotella and Dolosigranulum compared to those with the AA genotype." (PMID 36532717, 2022). "Following co‐culture, fibrocyte CD14 expression was restored with the potential to contribute to asthma pathogenesis via monocyte‐mediated processes dependent on the inflammatory milieu." (PMID 33209301, 2020). "Similar to 6A4G7, 17A1D10 inhibited D. pteronyssinus or Der p 2-stimulated IL-5 and IL-13 production in the MoDC/CD14− PBMC co-cultures of patients with asthma (respectively)." (PMID 31861989, 2019). "We have previously suggested that “% of CD4+CRTh2+T cells” and “% of CD14++CD16+PAR-2+ monocytes” are biomarkers of asthma severity." (PMID 31168305, 2019). "We have also shown that patients with severe asthma had increased PAR-2 expression on CD14++CD16+ (intermediate) monocytes in the peripheral blood compared to those with mild/moderate disease." (PMID 31168305, 2019). "Our study showed a significant increase in the percentage of the CD45+ population of blood cells that were monocytes (CD45+/CD14+) in patients with severe asthma compared to healthy controls." (PMID 31700522, 2019). "6A4G7 showed dose-dependent inhibition of D. pteronyssinus- or Der p 2-induced IL-5 production in MoDC/CD14− PBMC co-cultures was observed in all patients with asthma (respectively)." (PMID 31861989, 2019). "Of all differentially expressed miRNAs in peripheral blood CD14+ monocytes, 88 miRNAs were up-regulated and 41 miRNAs down-regulated in asthma children compared to controls." (PMID 30075787, 2018). "The percentages of PM2K+CD14+ and PM2K+CD14− cells were found to be significantly lower in subjects with asthma (mean ± SEM; 1.3 ± 0.1% and 1.3 ± 0.2%, respectively), when compared to those of normal healthy controls (1.6 ± 0.1% and 2.1 ± 0.2%, respectively)." (PMID 29343695, 2018). "Our results showed that the percentages of macrophage-like subsets (PM-2K+CD14+ and PM-2K+CD14−) were found to be significantly lower in subjects with asthma when compared to those of normal controls." (PMID 29343695, 2018). "mCD14 was mainly expressed by monocytes (>90% CD14+), and asthma produced a decrease in the percentage of CD14+ monocytes (and mean fluorescence intensity/MFI values), without changes between IMAA and MSAA." (PMID 29515128, 2018). "CD14+ monocytes contain precursors for macrophages and fibrocytes, known to be involved in regulating airway remodeling in human asthma and distinguishable by the PM-2K marker." (PMID 29343695, 2018). "CD14++CD16+ monocytes have also been reported to be increased in patients with severe asthma compared to mild/moderate asthmatics." (PMID 26658828, 2015). "We showed that PAR-2 expression on CD14++CD16+ monocytes are increased in patients with severe asthma." (PMID 26658828, 2015). "We showed that there are increased numbers of CD14++CD16+ monocytes expressing PAR-2 in the peripheral blood of patients with severe asthma compared to patients with mild/moderate disease." (PMID 26658828, 2015). "We aimed to investigate the effects of genetic variants of CD14 (−) and TLR4 (Asp299Gly, Thr399Ile) genes on asthma phenotypes in adults with asthma." (PMID 24524443, 2014).